CD5 (CD5 molecule)
Diseases named in the same sentence as CD5 in open-access papers (continued):
Sharing a sentence is not in itself a finding about the gene and the disease.
autoimmune disease (continued). "Thus, CD5 expressed on B-1a cells limits the production of excessive autoantibodies by B-1a cells and the negative regulation of BCR signaling by CD5 expression plays a vital role in preventing autoimmune disease development." (PMID 33374617, 2020). "During pregnancy, immune responses are suppressed under high estrogen levels, but they rapidly recover in the postpartum period, enhancing humoral immunity - possibly via increased autoantibody production from CD5+ B cells - and may trigger autoimmune diseases such as Graves' disease." (PMID 40605880, 2025). "Finally, human CD5+ B cells have not been clearly characterized, although they may act as additional diagnostic and therapeutic targets in several autoimmune diseases." (PMID 38179278, 2023). "As CD5/CD1d are regulatory facrors in mouse models of inflammation and CD24/CD38 are involved in human autoimmune diseases, we assessed the expression of these markers in CD19+ B cells via flow cytometry." (PMID 26378021, 2015). "Anti-CD5 CAR T cells have also been shown to be capable of invading the CNS, which could be directly applicable to autoimmune diseases with nervous system involvement." (PMID 39445021, 2024). "Applying this anti-CD5 and anti-CD7 CAR T cell treatment to autoimmune diseases with a strong T cell component could be a valuable treatment option." (PMID 39445021, 2024). "It is likely that FDA approval will come first for the use of anti-CD5 and anti-CD7 CAR T cell therapies for T cell leukemias and lymphomas; however, this could help pave the way for its future use in treating patients with severe T cell-mediated autoimmune diseases." (PMID 39445021, 2024). "Positive and negative functions were solely assigned to the LAT and CD5 signalosomes, respectively, whereas the CD6 signalosome conveys antithetical functions with implications for autoimmune diseases." (PMID 33125054, 2021).
follicular lymphoma (31 papers, 2011 to 2025). Follicular lymphoma is a form of non-Hodgkin lymphoma characterized by a proliferation of B cells whose nodular structure of follicular architecture is preserved. "CD5-positive follicular lymphoma (FL), although rare, has been described in a number of case reports." (PMID 40973845, 2025). "Our patient, a 76-year-old female with a history of previously treated stage IIIB follicular lymphoma, was found to have CD5+ DLBCL with leukemic transformation." (PMID 34327076, 2021). "Similarly to MCL, CD5+ follicular lymphoma (FL) and CD5+ marginal zone lymphoma (MZL) have also been shown to be associated with worse outcomes compared to their CD5- counterparts." (PMID 39410047, 2024). "Two patients had CD5-positive DLBCL (P15 and P2) in which one patient (P2) was accompanied with follicular lymphoma (FL)." (PMID 37925380, 2023). "Taken together, we show here that rituximab exerts beneficial effects especially in the subgroup of follicular lymphoma patients with low intrafollicular CD3, CD5, ZAP70 and CD8, and high CD56 and CD68 expression." (PMID 31273513, 2019). "We show here that rituximab exerts beneficial effects, especially in the subgroup of follicular lymphoma patients with low intrafollicular CD3, CD5, CD8, and ZAP70 and high CD56 and CD68 expression." (PMID 31273513, 2019). "In our case, although we considered the possibility of metastatic BC when analyzing the mesenteric biopsy, the immunohistochemical profile clearly revealed a nodular, low-grade (grade I) follicular lymphoma (CD20+, CD10+, BCL2+, CD23+, CD3−, CD5− and cyclin D1−)." (PMID 23419985, 2013). "The positive reaction for CD5 and negative reaction for CD10 and CD35 also exclude the possibility of follicular lymphoma, in which CD5 is negative and CD10 and CD35 (a marker of follicular dendritic cells) are positive." (PMID 22333190, 2012). "However, both SMZL and its mimickers can occasionally show an aberrant phenotype (e.g., expression of CD5 and/or CD23 in SMZL or lack of CD10 in follicular lymphomas (FL)), making a final diagnostic decision more difficult." (PMID 23064660, 2012). "CD5 negativity ruled out a small cell mantle lymphoma, and CD10 negativity ruled out a follicle center lymphoma." (PMID 36992464, 2023).
MALT lymphoma (31 papers, 2006 to 2026). An indolent, extranodal type of non-Hodgkin lymphoma composed of small B-lymphocytes (centrocyte-like cells). "Our study suggests that immunohistochemical expression of CD5, kappa, and lambda in oral MALT lymphoma have the risk of recurrence." (PMID 21892966, 2011). "Although some uncertainty remains, the histopathological findings and clinical course support the plausibility of a CD5-positive MALT lymphoma." (PMID 41262807, 2025). "Given the age and evolution of our patient’s MALT lymphoma, it can be considered indolent, although at the time of diagnosis the tumour cells were CD5-positive, in addition to kappa light chain expression." (PMID 34814897, 2021). "In contrast, CD5 positivity is unusual in MALT lymphomas except for some rare cases, that can even closely mimic CD." (PMID 24649966, 2014). "MALT lymphomas are usually CD5(-) and are characterized by the triad of (a) centrocyte-like cells, (b) small lymphoid cells, and (c) plasma cells, as described by Isaacson in 1987." (PMID 24891962, 2014). "Mikolaenko and Listinsky reported a case of CD5-positive MALT lymphoma with systemic involvement and Waldenstrom syndrome." (PMID 22333190, 2012). "The CD5 positivity in MALT lymphoma made the diagnosis difficult, and many differential diagnoses should be considered." (PMID 22333190, 2012). "In the oral cavity, previous report described that primary MALT lymphoma with the expression of CD5 occurred in the tongue." (PMID 21892966, 2011). "In oral MALT lymphoma, there are no reports that investigate immunohistochemical comparison of CD5, lambda, and kappa expression in primary and recurrent MALT lymphomas." (PMID 21892966, 2011). "We studied the case of a patient with a recurrent CD5 positive buccal MALT lymphoma in the oral cavity and compared the immunohistochemical expressions of CD5, lambda, and kappa between the primary and recurrent tumors." (PMID 21892966, 2011). "We first described the recurrence of CD5 positive MALT lymphoma in the oral cavity and compared the immunohistochemical expressions of CD5, lambda, and kappa between the primary and recurrent tumors." (PMID 21892966, 2011). "We first described the recurrence of CD5, lambda, and kappa positive MALT lymphoma in the oral cavity and recurrent MALT lymphoma showed weak positivity for CD5 and kappa and negativity for lambda." (PMID 21892966, 2011). "However, CD5-positive oral MALT lymphomas have been associated with disseminated forms, and several cases of MALT lymphomas of the oral mucosa expressing both kappa and lambda light chains have been correlated with aggressive behaviour and recurrence." (PMID 34814897, 2021). "Because the number of cases of CD5-positive MALT lymphoma is very small, its biological characteristics are unknown." (PMID 22333190, 2012). "The author herein reports the case of a CD5-positive pulmonary MALT lymphoma with good prognosis." (PMID 22333190, 2012). "Whether CD5 expression is relevant to the prognosis of patients with MALT lymphoma is controversial." (PMID 21892966, 2011). "Some researchers have documented expression of CD5 in MALT lymphomas, which is rare." (PMID 21892966, 2011). "This MALT lymphoma showed positivity for kappa but negativity for CD5." (PMID 21892966, 2011). "Our study raises the possibility to decide the therapeutic strategy whether oral MALT lymphoma expresses CD5, kappa, and lambda." (PMID 21892966, 2011). "However, we experienced that CD5 positive expression of MALT lymphoma in buccal mucosa occurred recurrence." (PMID 21892966, 2011). "A previous study revealed that MALT lymphomas that express CD5 tend to recur and disseminate." (PMID 21892966, 2011). "The significance, mechanism, and biological behaviors of CD5-positive MALT lymphoma are unknown." (PMID 22333190, 2012). "However, there are a few reports of CD5-positive MALT lymphoma of the lung and other organs." (PMID 22333190, 2012).
MALT lymphoma (continued). "MALT lymphoma cells immunohistochemically exhibit CD20+, CD79a+, CD5-, CD10-, CD23-, CD43+/-, and cyclin D1-." (PMID 36614921, 2022). "In immunohistochemistry, MALT lymphoma cells are CD20+, CD79a+, BCL2+, BCL6−, CD5−, CD10−, and CD23−." (PMID 35053607, 2022). "Typically, MALT lymphoma shows positivity for CD19, CD20, CD22, and CD79a, and negativity for CD3, CD5, CD10, CD23, BCL6, and cyclin D1." (PMID 33499258, 2021). "MALT lymphoma is positively stained for CD20, CD19, and it is negatively stained for CD5, CD10, and CD11c but it is positively stained for FMC7." (PMID 24511310, 2014). "Tumours analyzed were CD20+, cyclin D1−, CD23−, CD5−, Bcl-6−, CD43−, and CD10−, supporting the diagnosis of MALT lymphoma." (PMID 23420489, 2013). "Immunohistochemistry was in line with the current literature as both were at least CD20 positive and CD5 negative, which is a characteristic of most MALT lymphomas." (PMID 32908756, 2020). "MALT lymphomas express B-cell-associated antigens (CD20, CD22, and CD79a) and are negative for CD5, CD10, and CD3." (PMID 23476858, 2013). "Typically, neoplastic MALT lymphoma cells do not express CD5 although some researchers have reported that CD5 positive MALT lymphomas exist." (PMID 21892966, 2011). "We studied the case of a patient with a recurrent CD5 positive MALT lymphoma located in the buccal mucosa that showed weak, positive expression of CD5 and kappa and negative expression of lambda." (PMID 21892966, 2011). "MALT lymphomas are typically negative for CD5, CD10, BCL6 and cyclin D1." (PMID 34814897, 2021). "MCL cells coexpress CD20, CD5, and cyclin D1, unlike MALT lymphoma." (PMID 33499258, 2021). "Although almost cases generally lack of CD5 expression, a small subset of MALT lymphoma may express CD5." (PMID 25146638, 2014). "Although MALT lymphoma expressed CD5, this MALT lymphoma did not recur." (PMID 21892966, 2011). "Furthermore, previous studies have shown that CD5 positive MALT lymphomas are more prone to dissemination than those that do not express CD5." (PMID 21892966, 2011). "Immunophenotype can be determined either by immunohistochemistry or by flow cytometry, and MALT lymphomas are usually positive for CD19/20/22/79 and negative for CD5/10/23/BCL-6 and cyclin D1." (PMID 32908756, 2020). "MALT lymphoma is positively stained for CD20, CD19, and FMC7 and negatively stained for CD5, CD10, and CD11c." (PMID 24511310, 2014). "Typically, neoplastic MALT lymphoma cells express markers of B-cell lineage, and are negative for cyclin D1, CD23, CD10 and CD5, with rare exceptions." (PMID 23425357, 2013). "Typically, the neoplastic MALT lymphoma cells coexpress CD20+ and surface light-chain restriction but are negative for CD10 and CD5." (PMID 21892966, 2011). "Furthermore, MALT lymphomas produce positive stains for CD19 and FMC7, and negative for CD5, CD10, and CD11c." (PMID 39395994, 2024). "Furthermore, MALT lymphomas distinctively express CD21 and are negative for CD5, CD10, and cyclin D1, along with a low Ki-67 proliferation index." (PMID 39411128, 2024). "Although neoplastic MALT lymphoma cells do not express CD5, previous studies have shown that CD5 positive MALT lymphomas are more prone to dissemination than those that do not express CD5." (PMID 21892966, 2011).
T-cell lymphomas (31 papers, 2011 to 2026). "In systemic mature T-cell lymphomas, CD5 expression has been associated with higher clinical stage, bone marrow involvement, and poorer outcomes." (PMID 41226451, 2025). "This study confirmed that CD5 has a high prevalence in T-cell lymphomas and is associated with poor prognostic markers such as advanced age, bone marrow involvement, and poor functional status." (PMID 39410047, 2024). "Loss of CD5 expression has been reported in 43% of CD45+CD4+ T-cell lymphomas, whereas data concerning the expression of CD44 in different T-cell lymphoma subtypes are not available." (PMID 35448684, 2022). "Additionally, CD5 was associated with inferior survival in T-follicular cell lymphoma and adult T-cell lymphoma." (PMID 39410047, 2024). "Furthermore, promising target antigens, such as CD30 in Hodgkin ́s lymphoma and colon cancer, or CD5 on T-cell lymphoma, are co-expressed by healthy T cells creating the risk of durable damage to endogenous healthy T-cells upon targeting by conventional CAR T-cells." (PMID 36497099, 2022). "CD5-directed CAR T-cell therapy has shown promising antitumor activity in systemic T-cell lymphomas, with overall response rates approaching 60 percent and manageable toxicity." (PMID 41226451, 2025). "In a phase I clinical trial, fourteen patients with T-cell lymphoma underwent treatment with combination therapy consisting of a monoclonal antibody targeting CD5 and an immunotoxin." (PMID 38915099, 2024). "Given its high expression in TCLs, CD5 holds significant potential as a therapeutic target, particularly in nodal mature T-cell lymphomas." (PMID 39410047, 2024). "Since it is expressed in about 80% of T-ALLs and T-cell lymphomas, CD5 represents a surface marker of malignant T-cells." (PMID 36624522, 2023). "T-ALL and T-cell lymphoma cells were successfully eliminated in vitro, and disease progression was controlled in vivo in two different CD5+ T-ALL models." (PMID 36624522, 2023). "Among T-cell lymphomas, the aberrant expression of CD21 was significantly more frequent in TZL and the loss of CD5 and CD44 in T-NOS." (PMID 35448684, 2022). "CD5 is one of the most common surface markers of malignant T cells, expressed in around 80% of T-ALLs and T-cell lymphomas." (PMID 33081391, 2020). "CD5 expression is routinely examined during histological staining of T-cell lymphomas, and frequently harbors aberrant expression." (PMID 26566034, 2015). "CD5 is a cellular marker that has been associated with poor outcomes in other cancers but has not been well established in T-cell lymphoma." (PMID 39410047, 2024). "Our results therefore support a preferential use of CD5 as a target antigen for T-cell lymphomas." (PMID 35158792, 2022). "Approximately 10-15% of DLBCLs remain unclassifiable, and immunophenotyping and morphological analysis are critical to distinguish between B-cell and T-cell lymphomas, using markers such as CD3, CD5, CD20, and CD79a." (PMID 40959338, 2025). "The development of CD5-directed chimeric antigen receptor (CAR) T-cell therapy for relapsed and refractory T-cell lymphomas has generated substantial interest." (PMID 41226451, 2025). "We chose to investigate CD5 antigen as CD5 is highly expressed in the majority of T-ALL and T cell lymphoma, but also in a fraction of B cell tumor, such as CLL and MCL." (PMID 39462383, 2024). "A recent study has also proposed the inclusion of TRBC1 in a panel for T-cell lymphoma screening, including CD45, CD4, CD2, CD5, TCRγδ, CD7, CD3 and TRBC1." (PMID 40151427, 2024). "Meanwhile, in T-cell lymphoma, CD3+/CD21+ (63%), CD4-/CD8-(50%), CD5- (50%), and CD45- (50%) were the most common." (PMID 37908841, 2023). "In this work we performed a comparative analysis of the activity of CARs recognizing two established targets for T-cell lymphoma, CD3 and CD5 using a CAR-T or a CAR-NK framework." (PMID 35158792, 2022).
T-cell lymphomas (continued). "To investigate the best CAR framework to target T-cell lymphomas by NK effector cells, we compared the activity of a CAR-T and a CAR-NK framework to target CD3 and CD5 on T cells." (PMID 35158792, 2022). "Based on previous phenotypic analysis of patient samples, remaining T cells were identified as CD5+ CD7+ and T-cell lymphoma cells as CD5+ CD7‒." (PMID 35158792, 2022). "Flow cytometrically, abdominal fluid lymphocytes were highly positive for CD4, CD5, CD18, CD45, and MHC II, consistent with T cell lymphoma." (PMID 33602231, 2021). "A recently published phase I clinical trial of autologous CD5 CAR-T cells (NCT03081910) targeting relapsed/refractory T cell lymphomas has shown a tolerable safety profile, with no patient experiencing CRS of grade 3 or higher." (PMID 41295262, 2025). "Moreover, these CD5 CAR T cells were able to effectively eliminate T-ALL and T-cell lymphoma lines in vitro and to control disease progression in xenograft mouse models of T-ALL." (PMID 33081391, 2020). "Similarly to CD5 and CD7 molecules, CD3 was firstly evaluated as a therapeutic target in patients with T-cell lymphoma in studies using immunotoxin-loaded anti-CD3ε mAbs." (PMID 33081391, 2020). "CD4-positivity is the major immunohistochemical marker of primary CNS T-cell lymphoma, although other markers may include positive staining for pan T antigens (including CD3 and CD5)." (PMID 25789045, 2015). "Most mature T-cell lymphomas in our cohort were CD4-positive and were characterised by abnormal immunophenotypic features, including an altered expression of antigens of the T-cell lineage (e.g., CD2, CD3, CD5, and CD7), and abnormal expression of additional antigens such as CD279 and CD10." (PMID 39796028, 2024). "Importantly, this loss of CD5 did not compromise the cells’ effector function, which demonstrated preserved cytotoxicity in vitro and in vivo against preclinical models of T-ALL and T cell lymphoma." (PMID 41295262, 2025). "This tumor is a CD30+ T-cell lymphoma that is usually positive for CD2 and CD4 with variable expression of CD5, CD7, and CD8 but it is negative for EBER." (PMID 37958219, 2023). "Anaplastic large cell lymphoma is a CD30+ T-cell lymphoma, usually positive for CD2, CD4, and variable expression of CD5, CD7, and CD8 but negative for B-cell markers." (PMID 37958219, 2023).